Y_RNA (Y RNA )
Gene: Miscellaneous RNA gene on chromosome 2 (85,434,507 to 85,434,619, forward strand). Ensembl gene ENSG00000207207.
Homologues: Orthologues: chimpanzee Y_RNA (100% identical), guinea pig Y_RNA (92% identical), guinea pig Y_RNA (88% identical). Paralogues in human: RNY1 (92% identical), RNY1P11 (91% identical), Y_RNA (91% identical), Y_RNA (90% identical), Y_RNA (89% identical), Y_RNA (88% identical), RNY1P8 (88% identical), Y_RNA (87% identical), RNY1P7 (86% identical), Y_RNA (86% identical), RNY1P5 (85% identical), Y_RNA (85% identical), and 98 more.